MAGI2 (membrane associated guanylate kinase, WW and PDZ domain containing 2)
Diseases named in the same sentence as MAGI2 in open-access papers (continued):
Sharing a sentence is not in itself a finding about the gene and the disease.
glomerular disease (3 papers, 2021 to 2025). "We hypothesized whether MAGI2 could be a useful marker protein for discriminating between glomerular diseases in the histopathological diagnostic of kidney biopsies." (PMID 40563084, 2025). "In addition, reduced MAGI2 expression or mutations have been associated with glomerular disorders such as nephrotic syndrome in mice and humans." (PMID 34198584, 2021). "To summarize, we have shown that the expression of MAGI2 in the glomerulus is associated with the expression of nephrin regardless of the species investigated (human, mouse, rat, zebrafish) and that its expression is reduced in animal models of glomerulopathies." (PMID 40563084, 2025). "Having established that MAGI2 downregulation seems to be a stereotypical reaction in glomerular disease models, we evaluated its protein level in immunofluorescence analysis as a possible marker for glomerular diseases." (PMID 40563084, 2025). "In humans, a different regulation of MAGI2 in different glomerulopathies and, in particular, a marked downregulation of this protein in FSGS has been reported." (PMID 40563084, 2025). "We assessed the differential regulation of MAGI2 in glomerular disease animal models, and isolated glomerular dedifferentiation using immunostainings and LC–MS/MS tandem mass spectrometry." (PMID 40563084, 2025). "The proposed implication of MAGI2 in glomerulopathies is supported by both animal and human studies." (PMID 40563084, 2025). "MAGI-2 downregulation coincided with a reduced expression of slit-diaphragm backbone proteins in human glomerular disease, such as FSGS or IgA nephropathy." (PMID 41368354, 2025). "The regulation of MAGI2 in glomerulopathies appears to be a consequence of the process of podocyte dedifferentiation." (PMID 40563084, 2025). "To rapidly evaluate the glomerular Magi2 protein regulation in animal models of glomerular diseases, we applied a Deep-Learning network (U-Net) that was trained to segment immunofluorescence-stained glomeruli in confocal laser scanning micrographs." (PMID 40563084, 2025). "Furthermore, the same research group showed a differential MAGI2 abundance in biopsies of patients with different glomerulopathies using immunofluorescence, revealing a marked downregulation of this protein in FSGS." (PMID 40563084, 2025). "Furthermore, it has been shown that, as demonstrated for other scaffold proteins such as CD2AP, ZO-1 and NEPHRIN itself, the expression of MAGI2 is reduced in glomerulopathies." (PMID 40563084, 2025). "Since the dedifferentiation of podocytes plays a key role in the development of different types of glomerulopathies we wondered whether the regulation of Magi2 in the investigated models is a stereotypical consequence of podocyte damage in general or occurs due to podocyte dedifferentiation." (PMID 40563084, 2025). "To investigate whether glomerular MAGI2 abundance can be used as a marker for progression of glomerular disease we performed a correlation analysis of MAGI2 and eGFR in kidney biopsies of patients suffering from FSGS, after kidney transplantation, and in diabetic kidney disease." (PMID 40563084, 2025). "Besides this, not much is known about the expression change of MAGI2 in glomerular diseases or disease models." (PMID 40563084, 2025). "In vitro and in vivo studies using isolated glomeruli and mammalian animal models of glomerular disease, including DOCA-salt hypertension, nephrotoxic serum nephritis, and puromycin aminonucleoside nephropathy, demonstrated significant downregulation of MAGI2 in injured podocytes." (PMID 40563084, 2025).
infantile spasms (3 papers, 2020 to 2024). A rare epilepsy syndrome characterized by onset of epileptic spasms in infants between 2 and 12 months of age, and rarely up to 24 months. "In addition, three out of 14 patients with deletions including HIP1 and YWHAG, but not MAGI2, had infantile spasms, excluding one patient whose seizure type was not specified." (PMID 35481155, 2022).
ulcerative colitis (3 papers, 2017 to 2025). An inflammatory bowel disease involving the mucosal surface of the large intestine and rectum. "Allelic associations between TJ-related genes (F11R, MAGI1, MAGI2, MAGI3, PARD3, PTEN, and TJP1) and IBD, Crohn’s disease (CD), or ulcerative colitis (UC) were investigated." (PMID 28545409, 2017).
dementia (2 papers, 2009 to 2022). Loss of intellectual abilities interfering with an individual's social and occupational functions. "These loci are associated with several dementia-related genes, including PON1, AP2A2, MAGI2, POT1, ITGAX, PACSIN1, SLC2A8, and EIF4E." (PMID 35299244, 2022). "MAGI2, together with ATN1 (atrophin 1), has been implicated in Dentato-Rubral and PallidoLuysian Atrophy (DRPLA), a disease with a syndrome of myoclonic epilepsy, dementia, ataxia, and choreoathetosis." (PMID 19668339, 2009).
endometrial cancer (2 papers, 2025). Primary or metastatic malignant neoplasm involving the endometrium (mucous membrane that lines the endometrial cavity). "Utilizing cervical scrapings as a potential genetic material, coupled with the use of DNA hypermethylation in specific genes, including CDO1, CELF4, BHLHE22, POU4F3, MAGI2, CADM1, MAL, miR124-2, ZSCAN12, and GYPC, has been investigated for endometrial cancer detection." (PMID 41008854, 2025).
glomerulosclerosis (2 papers, 2021 to 2025). A hardening of the kidney glomerulus caused by scarring of the blood vessels. "MAGI2 KO mice, unlike MAGI1, cause neonatal lethality with observable kidney failure, while podocyte-specific MAGI2 deficiency promotes glomerulosclerosis several weeks after birth." (PMID 34198584, 2021). "Among these interactions, a nephrin-MAGI-2-RapGEF2-Rap1 signaling axis could be required for continuous SD-FA crosstalk, as podocyte-specific deletion of MAGI-2 or RapGEF2 leads to rapid glomerulosclerosis." (PMID 40457651, 2025).
hippocampal atrophy (2 papers, 2009 to 2022). "The variants in MAGI2 were previously associated with response to antidepressant treatment, as well as with hippocampal atrophy." (PMID 36685848, 2022). "Elucidating the roles of PRUNE2, MAGI2, ARSB and EFNA5 in the regulation of neurodevelopment, protein degradation, apoptosis and neuronal loss could enhance our understanding of hippocampal atrophy and AD." (PMID 19668339, 2009).
lung adenocarcinoma (2 papers, 2016 to 2021). A carcinoma that arises from the lung and is characterized by the presence of malignant glandular epithelial cells. "In addition, miR-134/487b/655 cluster is also reported to regulate TGF-β induced EMT and gefitinib resistance by targeting MAGI2 in lung adenocarcinoma cells." (PMID 27259866, 2016). "In a study in lung adenocarcinoma, different lung adenocarcinoma cell lines stimulated with TGF-β1 induced the overexpression of the microRNAs miR-134/487b/655, which in turn targeted MAGI2 for silencing." (PMID 34198584, 2021).
multiple myeloma (2 papers, 2021). "In multiple myeloma, MAGI2 is overexpressed and is significantly associated with unfavorable patient outcomes." (PMID 34503076, 2021). "Using a transcriptional CDK7 inhibitor, THZ1, coupled with H3K27ac ChlP-seq, we identified MAGI2 as a novel SE-associated gene of myeloma cells." (PMID 33579893, 2021). "A super-enhancer (large clusters of enhancers) in the MAGI2 gene is a driver of oncogenic phenotype in multiple myeloma and is further accentuated by binding the oncogenic MAF transcription factor." (PMID 34503076, 2021). "Overall, our results demonstrated that activation of SEs represent a common mechanism to activate novel cancer driver genes, and suggested a potential oncogenic role of MAGI2 in myeloma progression." (PMID 33579893, 2021). "Here, MAGI2 gene was identified as a functionally relevant oncogene in myeloma, and depression of the MAGI2-SE region markedly attenuated cell proliferation and induced cell apoptosis." (PMID 33579893, 2021). "Importantly, through profiling aberrantly epigenetic landscape and transcriptional program in myeloma cells, MAGI2 was identified as a novel SE-oncogene related to MM disease progression and poor survival." (PMID 33579893, 2021). "Importantly, the MAF/SE/MAGI2 regulatory circuit could potentially represent an attractive therapeutic target for future regenerative and cell-based myeloma therapies." (PMID 33579893, 2021).
acute pancreatitis (1 paper, 2013). An acute inflammatory process that leads to necrosis of the pancreatic parenchyma. "We performed a candidate gene study for MYO9B, PARD3 and MAGI2 looking for susceptibility to acute pancreatitis." (PMID 24386489, 2013). "We investigated genetic variation in MYO9B, PARD3 and MAGI2 for association with acute pancreatitis." (PMID 24386489, 2013). "Five single nucleotide polymorphisms (SNPs) in MYO9B, two SNPs in PARD3, and three SNPs in MAGI2 were studied in a Dutch cohort of 387 patients with acute pancreatitis and over 800 controls, and in a German cohort of 235 patients and 250 controls." (PMID 24386489, 2013). "None of the genetic variants of MAGI2 were associated with acute pancreatitis." (PMID 24386489, 2013).
allergic disease (1 paper, 2015). An immune response that occurs following re-exposure to an innocuous antigen, and that requires the presence of existing antibodies against that antigen. "MAGI2 was also reportedly associated with allergy in a GWAS of allergic diseases in a Russian population." (PMID 26734457, 2015).
amyloidosis (1 paper, 2024). A disorder characterized by the localized or diffuse accumulation of amyloid protein in various anatomic sites. "Additional astrocyte hub genes in the ETC, including NRXN1, CADM1, MACF1, MAGI2, LRP4, GJA1 and ADGRL3, have been identified as markers of a reactive astrocyte state, implicating them in amyloidosis, regulation of neuroinflammation, cellular interactions." (PMID 38913039, 2024).
Atrophy (1 paper, 2019). Any weakening or degeneration, especially through lack of use. "On the other hand, the expression of MAGI2 and RP4-587D13.2 is downregulated in the duodenum of active CD patients and persists even after more than 2 years on GFD and an apparent recovery from intestinal atrophy, supporting a constitutive alteration that could have a genetic origin." (PMID 31921880, 2019).
bladder cancer (1 paper, 2022). "Conversely, MAGI2.AS3 overexpression inhibited bladder cancer progression by regulating MAGI2/PTEN/EMT in 80 bladder cancer tissues." (PMID 35978835, 2022).
cervical cancer (1 paper, 2017). A primary or metastatic malignant neoplasm involving the cervix. "Here, we demonstrated a novel molecular mechanism by which HPV type 16 E6 oncoprotein induced Axl expression through the MAGI-2/PTEN/AKT signalling pathway in human cervical cancer cells." (PMID 28720772, 2017). "Collectively, the phosphorylation of AKT at ser 473 residues was upregulated by inhibition of MAGI-2/PTEN activity due to E6 silencing in cervical cancer." (PMID 28720772, 2017).
chronic kidney disease (1 paper, 2023). Impairment of the renal function secondary to chronic kidney damage persisting for three or more months. "MAGI2 identified by WGCNA is found to mediate cytoskeletal rearrangement of podocytes, the loss of which causes proteinuria and chronic kidney disease." (PMID 37656243, 2023).
colitis (1 paper, 2021). Inflammation of the colon. "In IBD, MAGI2, GNAI2, MIO9B, PTPN2, and CDH1 genes have been identified as tight junction assembly and barrier function regulators and were significantly associated with colitis." (PMID 33806347, 2021).
colon cancer (1 paper, 2024). "Specifically, we targeted large genes PRKG1, NEGR1, and MAGI2 in fibroblast line UM-HF1 (HF1) and FHIT and WWOX in lymphoblastoid line GM12878 and colon cancer line HCT116 as model systems for replication stress-associated SV formation." (PMID 39505880, 2024).
crescentic glomerulonephritis (1 paper, 2025). A histopathologic term for a pattern of diseases characterized by extensive crescent formation in the glomeruli; patients present clinically with rapid deterioration of renal function, and possible progression to end-stage renal failure within weeks or months. "In a rat model of crescentic glomerulonephritis (CGN) the downregulation of Magi2 was associated with an accumulation of Dendrin in the nucleus of podocytes." (PMID 40563084, 2025). "In the nephrotoxic serum nephritis (NTS) model, a murine model for crescentic glomerulonephritis, Magi2 was downregulated in comparison to control animals." (PMID 40563084, 2025).
delirium (1 paper, 2022). A disorder characterized by confusion; inattentiveness; disorientation; illusions; hallucinations; agitation; and in some instances autonomic nervous system overactivity. "Inhibiting TLR4/NF-κB/MAGI-2 signaling pathway could reduce postoperative delirium." (PMID 35294925, 2022).
dependence (1 paper, 2024). "Magi2 polymorphisms may also influence nicotine dependence in smokers; and 6) FK506 binding protein 5 (Fkbp5) which has been linked to DNAm changes in blood as discussed, but also modulates the effects of nicotine on the hypothalamic pituitary adrenal axis in female smokers." (PMID 38436597, 2024).
diabetes (1 paper, 2023). "Among these associations, rs113805659 in the MAGI2 gene was associated with non-insulin-dependent diabetes mellitus in African Americans." (PMID 36528847, 2023). "Furthermore, our disease gene association analysis highlighted rs113805659 in the MAGI2 gene in relation to diabetes in African Americans." (PMID 36528847, 2023).
diabetic kidney disease (1 paper, 2025). Progressive kidney disorder caused by vascular damage to the glomerular capillaries, in patients with diabetes mellitus. "MAGI2 mRNA levels were positively correlated with eGFR in isolated glomeruli of FSGS patients (Hodgin FSGS Glom dataset), in kidney biopsies of patients after kidney transplantation (Saint-Mezard Transplant Kidney), and in glomeruli isolated from diabetic kidney disease patients." (PMID 40563084, 2025).
gastric cancer (1 paper, 2024). A primary or metastatic malignant neoplasm involving the stomach. "While the hypermethylation of MAGI2 has been linked to gastric cancer tumorigenesis, our study is the first to identify an SNP in this gene associated with gastric cancer risk." (PMID 39408230, 2024).
infertile (1 paper, 2025). "Additionally, MAGI2, a gene where we found > 100 sites affected by the Added Sugar diet, exhibits differently methylated sites in both sperm and blood when comparing infertile patients and fertile controls." (PMID 39707713, 2025).
lung carcinoma (1 paper, 2015). "Moreover, it has been reported that miR-134/487b/665 cluster governed transforming growth factor-β (TGF-β)-mediated EMT and drug resistance to gefitinib by targeting membrance associated guanylate kinase inverted 2 (MAGI2) in lung cancer cells." (PMID 25638153, 2015).
minimal change disease (1 paper, 2025). "Human biopsy analyses revealed differential MAGI2 expression: it was increased in minimal change disease (MCD) patients but significantly decreased in primary, but not secondary FSGS cases." (PMID 40563084, 2025).
Nephropathy (1 paper, 2025). A nonspecific term referring to disease or damage of the kidneys. "Next, we evaluated glomerular Magi2 abundance in the puromycin aminonucleoside (PAN) nephropathy model." (PMID 40563084, 2025).
Obesity (1 paper, 2020). Accumulation of substantial excess body fat. "Still, whether through the regulation of BMSCs differentiation (FMN1 and BMPR1B), glucose metabolism (MAGI2), or initiation of the inflammatory process (SKAP2), these genes could be relevant to the development of obesity." (PMID 33003475, 2020).
pancreatitis (1 paper, 2020). Inflammation of the pancreas. "Certain genes, such as the myosin IXB (MYO9B) gene and its two close-connected adaptor genes, MAGI2 and PARD3, have been associated with pancreatitis as well as IBD." (PMID 32831829, 2020).
psychosis (1 paper, 2012). "We reasoned that if MAGI2 increases the risk for psychosis by virtue of its putative role as an indirect modulator of NMDA neurotransmission, it should also impact cognitive function associated with NMDA signaling, which has also been associated with psychosis." (PMID 22649501, 2012).
Stroke (1 paper, 2019). Sudden impairment of blood flow to a part of the brain due to occlusion or rupture of an artery to the brain. "Treatments with a human peptide that prevents PTEN association with MAGI-2 or MAST205 increased neuronal survival in multiple stroke models, in vitro." (PMID 31358730, 2019).
tumor (17 papers, 2015 to 2025). "MAGI2 hypermethylation disrupts Wnt/β‐catenin signaling, promoting tumor invasiveness, while HAND2 hypermethylation impairs progesterone signaling, contributing to hormone therapy resistance." (PMID 40528483, 2025). "Further studies have revealed that MAGI2 promotes PTEN (tumor suppressor) function to regulate several kinase signaling pathways." (PMID 32393302, 2020). "Six parameters, including age, pT category, tumor size, UICC stage, MAGI2, and RHBDD2, were tested by multivariate analysis using the Cox proportional hazard model." (PMID 37264057, 2023). "MAGI2, a scaffold protein required for PTEN, has also been identified as a target of miRNAs that are up‐regulated in tumours." (PMID 32672418, 2020). "Importantly, further investigations are warranted to identify the specific WW domain within MAGI2 that binds to KLF5, potentially offering a novel target for regulating tumor fatty acid synthesis." (PMID 39169280, 2024). "In addition, MAGI-2 is found in tumor studies to interact with PTEN via its PDZ2 domain and thereby stabilizes the structure of PTEN, increases its membrane trafficking, and enhances its inhibitory effect on Akt signaling and tumor pathogenesis." (PMID 31849609, 2019).
cancer (8 papers, 2020 to 2024). A tumor composed of atypical neoplastic, often pleomorphic cells that invade other tissues. "In addition to PCa, MAGI2 rearrangements with frame shift have been also identified in malignant melanoma, another cancer type in which PTEN loss is prevalent." (PMID 34198584, 2021). "Dysregulation of MAGI2 expression either via somatic genomic events or post-transcriptional regulation (by micro-RNAs) appears to affect PTEN activity in several cancer subtypes." (PMID 34198584, 2021). "Knocking out C9orf89, MAGI2, MLPH, or RHBDD2 in supporting cells reduced the ratio of apoptosis of cancer cells." (PMID 37264057, 2023). "The analyzed genes in this work (SOX17, MYOD1, MAGI2, CDH1, AJAP1, MGMT, CDH13, and RASSF1A) participate in essential biological processes to maintain cell normality, and there is sufficient evidence for their protective role against the development of cancer." (PMID 34991696, 2022). "In our study several interesting genes were upregulated in GFP+ alone including MAGI2, SALL4, and WRAP53, most which had been implicated in human cancers and with no known role in alphaviral infection or disease." (PMID 36680176, 2022). "Besides, artificial modulation of MAGI2 and PTEN was done to explore their function in ER stress and immune escape of cancer cells." (PMID 32672418, 2020).
gastrointestinal disorders (1 paper, 2019). "Polymorphisms in TJ-related genes MAGI2, PARD3, and MYO9B that potentially influence the homeostasis of the intestinal barrier have been associated with risk of gastrointestinal disorders like CD and IBD." (PMID 31921880, 2019).
hematological malignancies (1 paper, 2021). "As expected, MAGI2 was expressed much higher in MM specimens than normal bone marrow tissues (BM) and other non-MM hematological malignancies (data collected from Amazonia)." (PMID 33579893, 2021).